FOXO3 (forkhead box O3)
Diseases named in the same sentence as FOXO3 in open-access papers (continued):
Sharing a sentence is not in itself a finding about the gene and the disease.
cancer (continued). "Together with the observation that FOXO3 is the second most replicated gene associated with extreme human longevity suggests that pharmacological targeting of FOXO proteins can be a promising approach to treat cancer and other age-related diseases and extend life and health span." (PMID 37891184, 2023). "Hitherto, it remains totally unclear what causes these contrasting FOXO3 functions among different cancers, but the identification of FOXO3 modifications, co-factors and downstream targets involved in the control of different CSCs might provide informative clues." (PMID 29180117, 2018). "DDX5, in contrast, is generally described to have a consistently oncogenic effect through its regulation of the Wnt, Notch, mammalian target of rapamycin (mTOR), and forkhead box O3a (FOXO3a) pathways all involved in cancer progression." (PMID 39620586, 2025). "The protein is also influential in regulating FOXO3, a stress-response transcription factor, which can act as a tumor suppressor in certain cancers, halting aerobic glycolysis in tumors." (PMID 39858038, 2025). "In this review, we examine recently (from 2010 to 2024) reported plant extracts and phytochemicals with established anti-aging and anti-cancer effects via the activation of FOXO3 transcriptional factor." (PMID 39334758, 2024). "The mechanism underlying the cytotoxic activity of this compound has been documented: ergosterol peroxide stimulates Foxo3 activity by inhibiting pAKT and c-Myc and activating the pro-apoptotic proteins Puma and Bax to induce cancer cell death." (PMID 38444802, 2024). "The transcription factor Foxo3, a key determinant of cancer cell homeostasis, plays a dual role at the intersection of survival and apoptosis in response to metabolic stress and cancer chemotherapies." (PMID 39729481, 2024). "Studies indicate that upon AMPK activation, the Forkhead Box O3 (FOXO3) transcription factor is inhibited, resulting in a loss of GSC differentiation and likely preventing its transformation to fully malignant cancer cells." (PMID 38891882, 2024). "The reduced expression of FOXO3 has often been found in numerous human cancers with impairment of its anti-cancer capability." (PMID 39334758, 2024). "Among the 10 phosphopeptides upregulated in the high relapse-risk group, KIAA1522, DCK, FOXO3 and MYO9B are notable for their association with aggressive cancer phenotypes." (PMID 38745208, 2024). "The levels of FOXO3 protein expression were significantly different for major subclasses, individual cancer stages, and ages compared to normal tissue (P < 0.01)." (PMID 37976368, 2024). "Further research is needed to understand the full role of FOXO3 in aging and cancer to develop safe and effective ways to target FOXO3 for therapeutic purposes." (PMID 39334758, 2024). "Conclusively, this functional enrichment analysis indicates FOXO3’s pivotal role in diverse cancer and cancer-related signaling pathways." (PMID 37976368, 2024). "Compared with the other three FOXO members, FOXO3 seemed to be more predominant in controlling cancer progression, although they potentially regulate the same target genes." (PMID 38720807, 2024). "The AMPK/FOXO3 pathway is therefore a critical axis in preventing cancer cell growth and promoting cell death." (PMID 39334758, 2024). "In cancer, it inhibits the growth of cancer cells by inducing the expression of Foxo3 and inhibiting telomerase reverse transcriptase mRNA to activate mitochondrial-related proteins BNIP3 and BNIP3L." (PMID 38474452, 2024).
cancer (continued). "In our study on EC cells, we observed significant alterations in the expression levels of SIRT1 and FOXO3, consistent with reports in other cancer types." (PMID 39266959, 2024). "In contrast, the expressions of FOXC2 and FOXO3 mRNA were significantly downregulated in cancer tissues (P < .001, the difference was statistically significant)." (PMID 38608123, 2024). "FOXO3 is a promising target for interventions that aim to slow down the aging process and prevent cancer development." (PMID 39334758, 2024). "We further explored the expression of FOXO3 based on the individual cancer stage and age of the patients, which revealed its significant reduction across different stages and age groups of BC patients when compared to normal tissue (P < 0.01)." (PMID 37976368, 2024). "Along with the previous studies, our study indicates that the genetic variation of FOXO3 is complex, depending on cancer types." (PMID 38720807, 2024). "By utilizing Gene Set Enrichment Analysis (GSEA), we delved into the main Kyoto Encyclopedia of Genes and Genomes (KEGG) enrichment pathways of FOXO3, and the results suggested that FOXO3 was mainly involved in cancer-related pathways and the cell cycle." (PMID 37976368, 2024). "For PC, FOXO3 is a target of miR-223, and downregulation of FOXO3 by miR-233 leads to the proliferation, apoptosis, and cisplatin resistance in cancer cells." (PMID 38725864, 2024). "Our research results demonstrate that SIRT1 and FOXO3 can regulate mitophagy in EC cells, which differs slightly from reports in other cancers." (PMID 39266959, 2024). "For instance, it was found that the pharmacological inhibition of AKT and ERK promoted the activation of FOXO3, leading to apoptosis in several types of cancer." (PMID 39334758, 2024). "This review will concentrate on the potential anti-aging and anti-cancer effects of natural product extracts and phytochemicals activating FOXO3." (PMID 39334758, 2024). "Findings that FOXO1 and FOXO3 support stemness phenotypes in cancer cells likely have clinical significance and warrant further investigation." (PMID 37174744, 2023). "CircRNA Forkhead box O3 (Circ-Foxo3) formed from the exon 2 of FOXO3 plays important roles in cancer." (PMID 37020518, 2023). "It’s interesting to note that circ-Foxo3 expression was discovered to be considerably higher during cancer cell death." (PMID 37400900, 2023). "FOXO subfamily genes include FOXO1, FOXO3, and other subtypes, which mainly regulate metabolism, antioxidant stress, and cell cycle progression, and are mostly related to cancer and diseases of the immune system." (PMID 36819781, 2023). "FOXO3 has been reported to be a longevity-related gene in humans and an important regulator correlated with cancer drug resistance, lymphomagenesis, and Sirtuin signaling." (PMID 37573356, 2023). "FOXO1 and FOXO3 have been reported to regulate germ cells, neural stem cells, hematopoietic stem cells, muscle satellite cells, and cancer stem cells." (PMID 36881352, 2023). "FOXO3 was expressed at 1.12 0.01 (Mean+SE) in breast tissue with cancer growth compared to 1.99 0.07 (Mean+SE) in adjacent normal breast tissue (p 0.0001)." (PMID 36727057, 2022). "The varied roles of FOXO3 in cell cycle progression and tumorigenesis pose a great potential in effectively designing the therapeutic strategies for cancer treatment." (PMID 36727057, 2022). "With the increased understanding of FoxO3, it is also found to be responsible for the sensitization of cancer cells to chemotherapy, which is of great clinical significance." (PMID 35069908, 2022). "Suppression of cancer cell viability was explained by apoptosis and by up-regulating Foxo3 and Foxo3 downstream molecules Bim, Fas, and Fas L." (PMID 35408501, 2022). "For example, a high expression level of FOXO1 and FOXO3 has been found to be correlated with cancer metastasis and an MMP upregulation." (PMID 36555288, 2022).
cancer (continued). "Accordingly, FOXO3 inhibitionis a promising strategy for boosting antitumor immune responses andsuppressing FOXO3-mediated therapy resistance in cancer cells." (PMID 36188303, 2022). "Complex network of FOXO3 and its interaction with significant transcription factors make it a promising gene in cancer biology." (PMID 36727057, 2022). "The suppression of circ-FOXO3 promotes cancer proliferation as circ-FOXO3 binds with CDK2 and p21, thus inhibiting the cell cycle progression." (PMID 35205610, 2022). "Since FOXO3 acts as a transcription factor and it plays a crucial role in cell survival and proliferation, FOXO3 has been recognized as an important therapeutic target for cancer treatment." (PMID 35207737, 2022). "Among the targets of Sirt3 is the transcription factor Forkhead box O3 (FOXO3a), one of the key regulators of cancer cell homeostasis." (PMID 35938164, 2022). "For example, a high expression level of FOXO1 and FOXO3 has been found to be related to cancer metastasis and a matrix metalloproteinase (MMP) upregulation." (PMID 36555288, 2022). "It has been reported that the deregulation of FOXO3 expression is involved in cancer emergence and progression." (PMID 34771514, 2021). "As a transcription factor, FOXO3 plays a critical role in cancer progression via modulating gene activation." (PMID 34546972, 2021). "Among these TFs, we found various TFs functioned in cancer/normal stem-like cells such as Sox4, Foxo3 and Myc, indicating their potential regulation on BCSC heterogeneity." (PMID 34675206, 2021). "Regarded as an “OncomiR,” miR-155-5p shows features of oncogenicity by targeting SOCS1, FOXO3 in multiple types of cancer cells." (PMID 34131104, 2021). "Then siRNA-Akt was used to determine that L-carnitine ameliorated cancer cachexia via the Akt/FOXO3/MaFbx." (PMID 34724970, 2021). "FOXO3 was known as an inhibitor of cancer-related cell cycle progression and also contributed to the proliferation and metastasis of ESCC cells." (PMID 33747034, 2021). "FOXO3 is an ideal target for a variety of aging-related diseases, including cancer, degenerative diseases, and vascular aging." (PMID 35004893, 2021). "In this review, we summarize the current studies concerning circ-Foxo3 deregulation and the correlative mechanism in various human cancers." (PMID 33833780, 2021). "Collectively, data from these experiments demonstrated that sorafenib-resistant HCC cell lines are chemosensitive to regorafenib, which has been shown to partially exert its anti-cancer actions by targeting the pro-survival FOXO3-induced autophagy." (PMID 34769197, 2021). "In mammalians, the Foxo subfamily includes four genes of forkhead box-O transcription factors (Foxos), Foxo1, Foxo3, Foxo4, and Foxo6 that play a key role in cancer." (PMID 35178394, 2021). "In cancer research, one of the best studied circRNAs is generated from the tumor suppressor gene FOXO3, a member of the forkhead family of transcription factors that has been found to induce apoptosis of cancer cells through a variety of biological processes." (PMID 34368160, 2021). "In conclusion, our systematic review with meta-analysis has been the first to evaluate the potential of the transcription factor FOXO3 as a novel and functional biomarker in cancer and, more precisely, in HCC." (PMID 34771514, 2021). "A study used CRISPR-Cas9 knockout of FOXO3 (forkhead box O3) gene in U87MG cells, causing decreases in expression of the cancer stem cell markers Oct4 and Sox2." (PMID 34571991, 2021). "It was also reported that at high levels of Akt-mediated phosphorylation of FOXO3, full recovery and survival of cancer patients has a low rate." (PMID 33953834, 2021). "FOXO3 is now in a great interest in clinical research as a prognostic biomarker for cancer patients." (PMID 33953834, 2021). "FOXO-3 plays significant roles in biological processes, including cancer, and is actively involved in promoting apoptosis in a mitochondria-independent and -dependent manner." (PMID 34743742, 2021).
cancer (continued). "Recently, circ-Foxo3 was verified to play critical roles in the ceRNA network of various human cancers." (PMID 33833780, 2021). "This review mainly summarizes the recent knowledge about the characteristics of circ-Foxo3 in the biological behaviors and molecular mechanisms of human cancers." (PMID 33833780, 2021). "Circ-Foxo3 is highly expressed in normal tissues, while the downregulation of circ-Foxo3 usually occurs in the development of cancer." (PMID 33833780, 2021). "circFoxo3 is located in the cytoplasm and induces cancer cell apoptosis by inhibiting ubiquitylation of FOXO3." (PMID 33754062, 2021). "The downexpression of these miRNAs significantly reduced cancer cell proliferation and apoptosis by targeting FOXO-3, CLSPN, ACVR1B, E2F4 and PPP2CA and regulated cell cycle progression by targeting CDKN2A and FOXO-3." (PMID 34743742, 2021). "For example, FOXO3 promotes the malignant invasion of cancer cells by inducing the expression of matrix metalloproteinase and is required for leukemia stem cell maintenance." (PMID 33795838, 2021). "UCN-01, a drug currently used in clinical trials against cancer, inhibits Akt phosphorylation resulting in FOXO3 reactivation." (PMID 35004893, 2021). "In cancer cells, inactivation or knockdown of FOXO3 induces an EMT-like phenotype and thus promotes cell invasion and metastasis." (PMID 35008549, 2021). "In experimental studies, overexpression of FOXO3 inhibits the proliferation, tumorigenic potential, and invasiveness of cancer cells, while silencing of FOXO3 results in marked attenuation of protection against tumorigenesis." (PMID 34073605, 2021). "To begin to understand the similarity between FOXO3’s functions in aging and cancer, we generated FOXO3 transcriptional signatures of quiescent and activated NSCs from the RNA-seq dataset for further analysis." (PMID 36303712, 2021). "With the progression of cancer, the expression of Foxo3 decreased by inducing the activation of Akt and the silencing of PTEN." (PMID 33833780, 2021). "Collectively, our results provide strong evidence that PERK and GCN2 function cooperatively to play a pivotal role in cancer cell clonal renewal as well as cytotoxic drug resistance by suppressing FOXO3 expression via JNK." (PMID 32615282, 2020). "Among 4 mammalian FOXO members (FOXO1, -3, -4, -6), FOXO3 has a predominant role in controlling cancer development." (PMID 31903146, 2020). "FOXO3 and FOXM1 are also intimately associated with chemotherapeutic drug resistance and cancer stem cell properties." (PMID 32372224, 2020). "Apart from tissue specificity, circ-Foxo3 interacts with miRNAs in cancer cells and binds with proteins in cardiac tissue." (PMID 32781555, 2020). "CDK2 was noted in another research to form a complex substance with circ-Foxo3; this substance was abnormally expressed in cancer tissues in terms of participating in cell cycle regulation." (PMID 32699532, 2020). "Specifically, previous studies showed that FOXO3 plays an important role in the regulation of the cancer proliferation and apoptosis process." (PMID 33312341, 2020). "If FOXO3 serves as a functional target of miR‐96‐5p in cancer cell proliferation, re‐expression of FOXO3 in miR‐96‐5p‐overexpressing cells should be able to counter the effects of miR‐96‐5p." (PMID 32100957, 2020). "An earlier study suggests that SIRT2-mediated deacetylation promotes FOXO3 transactivation activity to reduce cellular ROS and induce cell death in cancer cells." (PMID 32372224, 2020). "As several studies point out the potential oncogenic properties of FOXO3 in different cancer types, pharmacological inhibition of FOXO3 is of great interest for novel therapeutic interventions in these cancers." (PMID 31591479, 2020).
cancer (continued). "Evidence showed that the AKT/FOXO3 pathway participates in the regulation of cell proliferation and apoptosis in carcinoma." (PMID 32760250, 2020). "This further suggests that SIRT1 and SIRT6 cooperate to set a threshold for FOXO3 acetylation in the cancer cells." (PMID 31357743, 2019). "We demonstrate that compounds S9 and its oxalate salt S9OX interfere with FOXO3 target promoter binding, gene transcription and modulate the physiologic program activated by FOXO3 in cancer cells." (PMID 31789593, 2019). "In cancer development, it has been supervised that elevation of AKT activity or deficiency of PTEN often resulted in down-regulation of Foxo3, and accelerated the formation of tumors." (PMID 31533653, 2019). "The tumour suppressive transcription factor FOXO3 promotes cell cycle arrest, senescence and cell death, and mediates the cytotoxic and cytostatic functions of cancer therapeutics." (PMID 31312024, 2019). "Our findings also suggest that SIRT1 and SIRT6 also play a coordinate role in fine-tuning FOXO3 acetylation and therefore lapatinib sensitivity by setting a threshold for the de-acetylation activity in both lapatinib sensitive and resistant cancer cells." (PMID 31357743, 2019). "For example, FOXO3 has been shown to enhance drug sensitivity, and to suppress the self-renewal and proliferation of cancer stem-like cells." (PMID 31013711, 2019). "Overall, the FOXO3 gene is involved in many signaling pathways and makes major contributions to several processes, including cancer development." (PMID 31294654, 2019). "This FOXO3-mediated PERK phosphorylation is likely to be mediated by the endogenous overactive ER stress signalling in these cancer cells." (PMID 31312024, 2019). "Several commercially available Akt inhibitors, like the used MK2206, act through FOXO3 activation are in pre- and clinical use to treat cancers." (PMID 31921181, 2019). "For example, circ-Foxo3 is down-regulated in cancer cells and is related to apoptosis and cell proliferation." (PMID 31519189, 2019). "The transcription factor FOXO3, a member of the forkhead box O (FOXO) superfamily, has been associated with elevated tumorigenicity in different cancers." (PMID 31861249, 2019). "That said, strong FoxO3 inhibition also slows / stops re-synthesis of p110, leading to a lengthened cell cycle (documented in cancer cells and tumors in vivo)." (PMID 30875364, 2019). "In consequence, our results also suggest that constitutive PERK activation can negatively regulate FOXO3 activity indirectly via AKT to promote cancer survival and drug resistance." (PMID 31312024, 2019). "FOXM1 is a potent oncogene negatively regulated by FOXO3 and contributes to cancer drug resistance through controlling many genes involved in cell proliferation, survival, DNA repair, and tubulin destabilization." (PMID 31727006, 2019). "By contrast, FOXO3 was shown to sensitize cancer cells to chemotherapy by mediating cytotoxic and cytostatic effects of cancer therapeutics such as cisplatin (CDDP)." (PMID 31491919, 2019). "In cancer cells, FOXO3 has been reported to repress VegfA expression by directly binding to the VegfA promoter region." (PMID 30842454, 2019). "In contrast, ESR1 is upregulated for survival by interacting with the transcriptionally active FOXO3 gene through Eleanors, which represents cancer robustness." (PMID 31439835, 2019). "In consequence, FOXO3 is often downregulated as an adaptive response in cancer and particularly in chemotherapeutic drug-resistant cells." (PMID 31312024, 2019). "Although the interaction between genes for growth (ESR1) and apoptosis (FOXO3) appeared contradictory at first, apoptotic activity is frequently enhanced in cancer, both in cultured cell lines and patient cells." (PMID 31439835, 2019). "Over the past decade, the relationship between FOXO3 and cancer cell development has been investigated." (PMID 31540495, 2019).